CASP2 (caspase 2)
Diseases named in the same sentence as CASP2 in open-access papers (continued):
Sharing a sentence is not in itself a finding about the gene and the disease.
Pachygyria (1 paper, 2024). Pachygyria is a malformation of cortical development with abnormally wide gyri with sulci 1,5-3 cm apart and abnormally thick cortex measuring more than 5 mm (radiological definition). "In summary, we present seven patients with CASP2-related DD/ID and all patients for whom brain MRIs were available have anterior-predominant LIS and pachygyria in neuroimaging, similar to previously reported CRADD and PIDD1 patients." (PMID 37880421, 2024).
pancreatic carcinoma (1 paper, 2014). "It was shown that in human pancreatic carcinoma cells bortezomib disrupted lysosomes with release of cathepsin B to the cytosol where it cleaved caspase-2 and induced mitochondrial apoptotic pathway." (PMID 25310712, 2014).
papillary thyroid carcinoma (1 paper, 2022). "High expression of SNX5 was demonstrated in well-differentiated papillary thyroid carcinoma, and co-expression of SNX5 and caspase-2 was also found in thyroid epithelial cells." (PMID 35715463, 2022).
renal cell carcinoma (1 paper, 2015). "We recently reported that ROS trigger DNA damage, thereby leading to activation of caspase-2 in renal cell carcinoma lines." (PMID 26000607, 2015).
Salmonella Infections (1 paper, 2013). Infections with bacteria of the genus SALMONELLA. "Interestingly, caspase-2 contains a CARD domain and has been shown to mediate caspase-1 activation during Salmonella infections." (PMID 24350060, 2013).
skin tumor (1 paper, 2014). "Importantly, caspase-2 knockout mice were more prone to develop skin tumor lesions in response to Ras activation, these skin tumor lesions requiring escape from OIS as previously demonstrated in our laboratory." (PMID 25114039, 2014).
tauopathies (1 paper, 2024). "Caspase-2-cleaved tau reversibly impairs memory function in animal and cellular models of tauopathies due to accumulation in dendritic spines and attenuation of synaptic transmission." (PMID 38419122, 2024). "Incidentally, caspase-2-cleaved tau fragments have been found in other diseases such as Lewy body disease, and Huntington’s disease, showing that they are not specific to AD or tauopathies." (PMID 38419122, 2024).
temporal lobe epilepsy (1 paper, 2021). A localization-related (focal) form of epilepsy characterized by recurrent seizures that arise from foci within the temporal lobe, most commonly from its mesial aspect. "Moreover, caspase 2 is hyperexpressed in hippocampal neurons of subjects operated for drug refractory temporal lobe epilepsy and it is required for the synaptic changes observed in the human amyloid precursor protein transgenic mice (J20)." (PMID 34163010, 2021).
Testicular atrophy (1 paper, 2011). Wasting (atrophy) of the testicle (the male gonad) manifested by a decrease in size and potentially by a loss of fertility. "However, pathological phenotypes of HD including specific striatal volume loss and testicular degeneration are not rescued in the casp-2-/- mice." (PMID 21854568, 2011).
uterine corpus endometrial carcinoma (1 paper, 2020). A endometrial carcinoma (disease) that involves the body of uterus. "The Arg-378Trp mutation in caspase-2, or Arg-207Stop in caspase-3, or Arg-220Trp in caspase-6 were found in uterine corpus endometrial carcinoma and is probably involved in apoptotic cell death disturbances and tumorogenesis." (PMID 33011746, 2020).
tumor (78 papers, 2007 to 2026). "In our cohort, elevated CASP2 mRNA in COAD patients is potentially linked to the tumor cell senescent state at sampling." (PMID 41614944, 2026). "Levels of TNFα were also further increased by 18 months of age in tumor-free mice, consistent with a chronic inflammatory phenotype observed in caspase-2-deficient mice." (PMID 41477850, 2026). "Mechanistically, the tumor suppressor function of caspase-2 has been attributed to its ability to cause apoptotic removal of aneuploid cells upon replicative stress." (PMID 38429264, 2024). "The action of docetaxel on tumor cells, after the polymerization of microtubules, causes mitotic catastrophe and caspase-2 and -3-dependent apoptosis." (PMID 36361635, 2022). "In a mouse TH-MYC neuroblastoma tumor model, the loss of caspase-2 was found to delay tumorigenesis." (PMID 35741016, 2022). "Employing a model of mammary tumorigenesis, caspase-2 deficiency leads to higher tumor incidence and decreased survival of mice." (PMID 35444189, 2022). "Here, we provide evidence that p54nrb as a caspase-2 substrate can play a key role in orchestrating cell death susceptibility and long term tumor survival in distinct tumor types." (PMID 35444189, 2022). "Caspase-2 has also been implicated in ageing-related metabolic changes in mice and has been shown to negatively regulate necroptosis in tumor cells." (PMID 35444189, 2022). "In mouse models employing caspase-2 deficiency, a tumor suppressive effect of caspase-2 has been reported by several laboratories." (PMID 33854186, 2021). "Previous studies using knockout (KO) mice have demonstrated that caspase-2 deficiency promotes tumour development following replicative or oncogenic stress." (PMID 32811973, 2021). "Consistent with the unclear apoptotic function for caspase-2, few apoptotic defects are reported in caspase-2-deficient tumor models." (PMID 33425918, 2020). "This suggests that loss of caspase-2 not only increased overall tumor incidence but also increased the rate of tumorigenesis." (PMID 33425918, 2020). "A prevalent phenotype in caspase-2-deficient tumor models results from features associated with increased genomic instability." (PMID 33425918, 2020). "The cell-death receptor-associated caspase-2-dependent cell death reflects its tumor suppressor function." (PMID 32438737, 2020). "Dual caspase-2/ATM deficiency increased the incidence of tumor formation from 31% in control Atm-deficient mice to nearly 64% in Casp2/Atm double knockout mice." (PMID 33425918, 2020). "In a model of c-Myc-induced lymphomagenesis, loss of caspase-2 accelerated tumor growth, but loss of PIDD1 suppressed tumor formation, suggesting that caspase-2 does not depend on PIDD1 to suppress tumors." (PMID 33425918, 2020). "Data from various tumor models implicate that loss of caspase-2 facilitates tumor growth and contributes to the development of cancer." (PMID 31366165, 2019). "Caspase-2 has several functions in the cell and among others can influence tumor cells, and metabolic pathways including those linked to lipid metabolism." (PMID 31296846, 2019). "This gene has been assigned with a tumour suppressor role in cancer, a role that is connected to cell death but also with cellular stress and transformation; moreover, loss of CASP2 promotes carcinogenesis in in vivo models of malignant pathologies." (PMID 30857282, 2019). "In this study, we comparatively analyzed the transcriptomes of Casp2−/− tumors from EμMyc and Th-MYCN mice to identify changes in transcriptional tumor networks that are influenced by caspase-2 deficiency." (PMID 30670683, 2019). "The pathophysiological relevance of caspase-2 is underscored by data from animal tumor models demonstrating that the loss of caspase-2 critically contributes to tumor development." (PMID 31842382, 2019).
tumor (continued). "One commonly observed feature of caspase-2-deficient tumours and MEFs is enhanced aneuploidy, likely because of reduced or inefficient apoptotic removal of aberrant cells in the absence of caspase-2." (PMID 27906175, 2016). "Caspase-2-deficient mice develop normally but show ageing-related traits and, when challenged by oncogenic stimuli or certain stress, show enhanced tumour development, often accompanied by extensive aneuploidy." (PMID 27906175, 2016). "Instead, we found that the aneuploid cells present in the Caspase-2-deficient tumors showed a greater variation of chromosome numbers in the same tumor sample." (PMID 25857265, 2015). "Eμ-Myc transgenic B-cell tumors deficient for Caspase-2 did show a higher variation of chromosome numbers within individual tumor samples." (PMID 25857265, 2015). "Taken together, these studies support a role for RAIDD in drug-induced cancer cell death as well as in tumor suppression, most likely linked to its role as a direct activator of Caspase-2." (PMID 25857265, 2015). "Given that caspase-2 has been shown to reside in the nucleus and possess a tumour-suppressor function, the cancer-associated transcription factor Runx1 was an attractive candidate substrate for this protease." (PMID 27919034, 2014). "In the light of data revealing a tumour-suppressor role for caspase-2, we were intrigued by the identification of the cancer-associated proteins Runx1 and 3 as potential caspase-2 substrates." (PMID 27919034, 2014). "Consistent with a tumour-suppressor function, caspase-2 deletion, mutation or down-regulation have been reported in some human cancers." (PMID 27919034, 2014). "In mammary tumors of transgenic mice overexpressing ErbB-2 or PyMT, however, a DDR was not detectable, and it would therefore be interesting to assess the influence of caspase-2 loss in these tumor models." (PMID 24281211, 2010). "Genetic deletion of caspase-2 leads to increased tumor susceptibility in vivo." (PMID 35444189, 2022). "In addition, we have identified aberrant expression of several oncogenes and tumor suppressor genes that potentially co-operate with Casp2 loss, to determine tumor outcome." (PMID 30670683, 2019). "While many of these genes may play co-operating roles with Casp2 loss to enhance EμMyc-mediated lymphomagenesis, aberrant expression of some genes are likely a consequence of enhanced tumor growth caused by Casp2 loss." (PMID 30670683, 2019). "Collectively, our work provides a possible explanation for the reported cellular and systemic defects caused by loss of Caspase-2, including increased aneuploidy and heightened tumor susceptibility upon oncogenic stress, metabolic dysfunction, or proteotoxic stress and premature aging." (PMID 28130345, 2017). "We also conclude that caspase 2, in an AR-dependent fashion, may be a specific intracellular switch for the regulation of the susceptibility of tumour cells." (PMID 17262078, 2007).
tumor (continued). "In this study, we describe p54nrb as a nuclear caspase-2 substrate and we demonstrate that disruption of p54nrb leads to expressional changes of tumorigenic genes and decreased stress tolerance resulting in increased cell death susceptibility in human tumor cells." (PMID 35444189, 2022). "In addition to caspase-2, other caspases such as caspase-6, -7, and -8 also act as tumor suppressors, although the genetic mechanisms underlying the activation of these caspases and their relevance to tumor suppression remain to be elucidated." (PMID 32438737, 2020). "Although caspase-2 null mice are viable and display limited, tissue-specific cell death defects, more recent observations with knockout animals revealed an increased susceptibility to tumor formation induced by overexpression of specific oncogenes, suggesting a tumor suppressive role of caspase-2." (PMID 31366165, 2019). "In addition, Caspase 2 and Ei24 act as tumor suppressor genes, and their loss may contribute to tumor metastasis." (PMID 28794853, 2017). "For total tumor incidence, [Casp2+/+ versus Casp2−/−: χ2(1, N = 40) = 3.916, *P = 0.048] and [Casp2+/+ versus Casp2C320S: χ2(1, N = 44) = 13.333, ***P = 0.0003]." (PMID 41477850, 2026). "Further, increases were observed in the >18-month-old tumor-free cohort with a higher trend for liver damage markers in Casp2C320S mice compared to Casp2+/+ mice." (PMID 41477850, 2026). "Notably, we demonstrate that early onset of hyperpolyploidy, karyomegaly, and aneuploidy in caspase-2-deficient young mice correlates with dysregulation of a distinct set of cell cycle proteins linked to heightened liver pathology and spontaneous age-related tumor formation." (PMID 41477850, 2026). "A role for caspase-2 in controlling aneuploidy and polyploidy has been demonstrated in various cell lines, primary cell types, and mouse tissues and is a proposed mechanism for caspase-2-mediated tumor suppression." (PMID 41477850, 2026). "The apoptotic caspase, caspase-2, has an important function in limiting aneuploidy and polyploidy, as part of its roles in apoptosis, tumor suppression, and aging." (PMID 41477850, 2026). "While caspase-2 protects against diet-induced hepatic injury, it also acts as a tumor suppressor by controlling genomic instability and oxidative stress." (PMID 41477850, 2026). "Caspase 2 was reported to be the direct target of miR-183, by which the inhibition of miR-183 expression resulted in an increased CASP2 expression to inhibit the proliferation and tumor growth of NCI-H441 cells." (PMID 40141140, 2025). "Caspase-2 is the most conserved member of the caspase family and is well-studied for its role as a tumor suppressor under conditions of oncogenic or replicative stress." (PMID 38429264, 2024). "We also profiled caspase-2 expression in a panel of 10 mouse tumor cell lines and observed highly variable expression levels." (PMID 38676703, 2024). "Here, we demonstrate that BID levels regulate an AURKB/CASP-2 mitotic checkpoint that determines the fate of tumor cells when the SAC is overridden; senescence if BID expression is low but cell death in case of high BID levels." (PMID 37443114, 2023). "The fate of tumor cells after SAC abrogation is driven by an AURKB/ CASP-2 signaling mechanism, regulated by BID levels." (PMID 37443114, 2023).
tumor (continued). "Earlier results from us and others have demonstrated that caspase-2 plays a role in promoting and executing DNA damage-induced apoptosis in various tumor cell systems." (PMID 35690610, 2022). "In the current study, only nine apoptotic genes were included in the array, with caspase-2 and caspase-7 being the most expressed in tumour lines." (PMID 36142793, 2022). "Given the complexity of caspase-2 and the vital regulation of miRNAs in tumor progression, an increasing number of studies have been focusing on these two intriguing regulators in cancer development." (PMID 36171196, 2022). "As aforesaid, in the context of cancer progression, the essence of caspase-2 as a tumor suppressor highlights it as a vital target of miRNAs in the modulation of cancer." (PMID 36171196, 2022). "Alongside caspase-8, caspase-2 is the only caspase that has a demonstrated role in tumor suppression." (PMID 35444189, 2022). "In contrast, recent studies highlight the relevance of caspase-2 in regulating cell death independent functions in tumor suppression." (PMID 35444189, 2022). "How caspase-2 contributes to tumor suppression at the downstream signaling level is still unanswered." (PMID 35444189, 2022). "Inhibition of caspase-2, a downstream target of miR-383, was shown to restore the tumor suppressive effect induced by miR-383 down-regulation." (PMID 36171196, 2022). "Intriguingly, Atm-/-caspase-2-/-mice showed drastically increased tumor development with an increased extensive aneuploidy compared with Atm-/-mice, suggesting that caspase-2 has a protective role against aneuploidy." (PMID 34069817, 2021). "These conflicting observations indicated that caspase-2 has a tissue- and context-specific role in tumorigenesis, with concomitant aberration of driver oncogenes or tumor suppressors." (PMID 34069817, 2021). "v. injection into tumor-bearing mice, such a photosensitizer was preferentially accumulated in the tumor region, and induced the activation of golgi caspase-2 in A-549 cells and triggered apoptosis." (PMID 34277702, 2021). "Here, we review these recent observations and their implications in caspase-2-mediated cellular death, senescence, and tumor suppression." (PMID 33854186, 2021). "It is unclear how caspase-2 regulates these opposing functions, which has made the mechanism of tumor suppression by caspase-2 difficult to determine." (PMID 33425918, 2020). "Although the pro- vs. anti-tumor impacts of ER stress are still debated in the field, it is possible that caspase-2 has been overlooked as a contributor to cell death resulting from this phenotype." (PMID 33425918, 2020). "MDM2 is a caspase-2 substrate that has the potential to reveal the mechanism of tumor suppression by caspase-2 due to its own ability to regulate both apoptosis and cell cycle." (PMID 33425918, 2020). "This review highlights the known substrates of caspase-2 with a special focus on their functional relevance to caspase-2’s role as a tumor suppressor." (PMID 33425918, 2020). "Further, the average age of tumor onset was decreased in Casp2/Atm double knockout mice compared to Atm knockout alone." (PMID 33425918, 2020). "These distinct effects of caspase-2 on different tumor types strongly suggests that caspase-2 functions in different capacities depending on the cellular context." (PMID 33425918, 2020).